PNLIPRP3 (pancreatic lipase related protein 3)
Description:
Hydrolyzes triglycerides into diglycerides and subsequently into monoglycerides and free fatty acids.
Tractability: Small molecule: it belongs to a druggable protein family. Antibody: UniProt places it where antibodies can reach, with high confidence; UniProt predicts a signal peptide or a membrane-spanning region; its Gene Ontology location is reachable by antibodies, with medium confidence.
Gene: Protein-coding gene on chromosome 10 (116,427,847 to 116,477,957, forward strand). Ensembl gene ENSG00000203837.
Subcellular location: Secreted
Pathways (Reactome):
Digestion and absorption: Digestion of dietary lipid
Gene Ontology:
Molecular function: lipoprotein lipase activity; phospholipase A1 activity; carboxylic ester hydrolase activity; lipase activity; triacylglycerol lipase activity
Biological process: cholesterol homeostasis; fatty acid biosynthetic process; high-density lipoprotein particle remodeling; triglyceride catabolic process; lipid metabolic process
Cellular component: extracellular region
Genetic constraint (gnomAD): Loss-of-function variants: 50 observed, 43.24 expected, observed/expected ratio (o/e) 1.16, 90% interval 0.92 to 1.46. The upper end of that interval is the gene's LOEUF score, 1.46, which puts it in group 6 of 6, group 1 being the genes least tolerant of losing a copy. Missense variants: 542 observed, 523.7 expected, observed/expected ratio (o/e) 1.03, 90% interval 0.96 to 1.11. Synonymous variants: 172 observed, 170.96 expected, observed/expected ratio (o/e) 1.01, 90% interval 0.89 to 1.14.
Homologues: Orthologues: chimpanzee PNLIPRP3 (99% identical), macaque PNLIPRP3 (96% identical), pig PNLIPRP3 (80% identical), dog PNLIPRP3 (80% identical), Drosophila melanogaster CG6847 (26% identical), zebrafish lipib (25% identical), Drosophila melanogaster CG13282 (25% identical), Drosophila melanogaster CG7367 (24% identical), Drosophila melanogaster CG34447 (23% identical), Drosophila melanogaster CG14034 (22% identical), Drosophila melanogaster CG34448 (22% identical), Drosophila melanogaster CG6675 (22% identical), and 19 more. Paralogues in human: PNLIPRP1 (49% identical), PNLIPRP2 (48% identical), PNLIP (46% identical), LIPC (29% identical), LIPG (28% identical), LIPI (27% identical), LIPH (26% identical), LPL (25% identical), PLA1A (23% identical).
Diseases named in the same sentence as PNLIPRP3 in open-access papers:
PNLIPRP3 is named in the same sentence as 6 diseases in open-access papers, as found by Europe PMC text mining. Sharing a sentence is not in itself a finding about the gene and the disease. The quoted sentences say what the papers report.
Flavivirus Infections (1 paper, 2023). Infections with viruses of the genus FLAVIVIRUS, family FLAVIVIRIDAE. "Only one gene, PNLIPRP3, showed dysregulated expression levels (overexpression) as well as dysregulated alternative splicing in all three Flavivirus infections (the same three ASEs in KUNV and ZIKV infection, but only one of the three ASEs in YFV infection)." (PMID 37515107, 2023).
glioma (1 paper, 2021). A benign or malignant brain and spinal cord tumor that arises from glial cells (astrocytes, oligodendrocytes, ependymal cells). "We note from the literature that the peptide glioma growth inhibitor hHSS1/C19orf63/EMC10 also upregulates PNLIPRP3 very highly in U87 cells." (PMID 34359681, 2021). "From its entry in the Human Protein Atlas, PNLIPRP3 has not been associated with either a favorable or unfavorable prognosis in glioma and is not expressed even at low levels in most normal human tissues." (PMID 34359681, 2021).
hepatocellular carcinoma (1 paper, 2021). A malignant tumor that arises from hepatocytes. "The PNLIPRP3 gene encodes the protein Pancreatic Lipase Related Protein 3 (LIPR3), a rarely studied gene as judged by PubMed citation, previously observed as overexpressed in hepatocellular carcinoma." (PMID 34359681, 2021).
infection (1 paper, 2025). The state of being infected such as from the introduction of a foreign agent such as serum, vaccine, antigenic substance or organism. "Pro-inflammatory cytokines and chemokines, including TNF-α, CSF3 and CCL4, were upregulated in both infection groups, alongside genes involved in immune cell adhesion and inflammatory responses (SELE), as well as stress response mediators such as HSP70 and PNLIPRP3." (PMID 41435987, 2025).
PNLIPRP3 also shares sentences with these, for which no sentence is quoted: cancer (1 paper); ZIKV infection (1).